MATN1 (matrilin 1)
Description:
A major component of the extracellular matrix of non-articular cartilage (By similarity). Binds to type 2 collagens and forms long concatenated protein networks as part of the extracellular matrix (By similarity). Required for the network-like organization and bundling of collagen fibrils surrounding chondrocytes in the zones of maturation and hypertrophy (By similarity). Required for mechanotransduction and adaption to mechanical loading in cartilage chondrocytes, resulting in an increase in expression of the extracellular matrix components ACAN and COL2A1 (By similarity). Acts as a moderator of angiogenesis in response to injury (By similarity).
Synonyms: CMP; CRTM
Tractability: Antibody: its Gene Ontology location is reachable by antibodies, with high confidence; UniProt places it where antibodies can reach, with medium confidence; UniProt predicts a signal peptide or a membrane-spanning region.
Gene: Protein-coding gene on chromosome 1 (30,711,277 to 30,723,585, reverse strand). Ensembl gene ENSG00000162510.
Subcellular location: Secreted, extracellular space, extracellular matrix
Pathways (Reactome):
Extracellular matrix organization: ECM proteoglycans
Gene Ontology:
Molecular function: protein binding; extracellular matrix structural constituent; calcium ion binding
Biological process: extracellular matrix organization; protein-containing complex assembly
Cellular component: matrilin complex; extracellular matrix; extracellular region; non-collagenous component of interstitial matrix
Genetic constraint (gnomAD): Loss-of-function variants: 34 observed, 40.39 expected, observed/expected ratio (o/e) 0.84, 90% interval 0.64 to 1.12. The upper end of that interval is the gene's LOEUF score, 1.12, which puts it in group 4 of 6, group 1 being the genes least tolerant of losing a copy. Missense variants: 602 observed, 648.01 expected, observed/expected ratio (o/e) 0.93, 90% interval 0.87 to 0.99. Synonymous variants: 264 observed, 270.91 expected, observed/expected ratio (o/e) 0.97, 90% interval 0.88 to 1.08.
Homologues: Orthologues: chimpanzee MATN1 (99% identical), macaque MATN1 (98% identical), dog MATN1 (93% identical), pig MATN1 (92% identical), guinea pig MATN1 (91% identical), mouse Matn1 (90% identical), rat Matn1 (90% identical), rabbit MATN1 (89% identical), tropical clawed frog matn1 (71% identical), zebrafish matn1 (67% identical). Paralogues in human: MATN4 (50% identical), MATN2 (50% identical), MATN3 (33% identical), COL12A1 (30% identical), COL14A1 (30% identical), COL6A3 (28% identical), COL6A6 (26% identical), VWA2 (25% identical), COCH (24% identical), COL6A5 (24% identical), VIT (13% identical), VWA1 (12% identical).
Diseases named in the same sentence as MATN1 in open-access papers:
MATN1 is named in the same sentence as 24 diseases in open-access papers, as found by Europe PMC text mining. Sharing a sentence is not in itself a finding about the gene and the disease. The quoted sentences say what the papers report.
breast carcinoma (5 papers, 2021 to 2023). "GWAS that implicate BNC2-associated alleles with adolescent idiopathic scoliosis also implicate other ECM-associated genes and cytokines that we also find to be under BNC2 control in our breast cancer system (MATN1, MMP9, SOX9, IL-6 as examples)." (PMID 37536977, 2023).
chondrodysplasia (4 papers, 2008 to 2025). "Related to collagen structure is the complex formed between DCN and matrilin-1, a protein involved in matrix assembly, whose relative, matrilin-3, has been linked to certain chondrodysplasias." (PMID 40001470, 2025). "Matrilin-1 is involved in a variety of inherited chondrodysplasia." (PMID 24741569, 2014). "We hypothesized that deletion of matrilin 1, which would abolish the formation of matrilin 1/matrilin 3 heterotetramers, would also eliminate the secretion of mutant matrilin 3 into the ECM and increase the severity of chondrodysplasia in mice with the Matn3 V194D mutation." (PMID 22083516, 2012).
relapsing polychondritis (4 papers, 2014 to 2020). A rare, clinically heterogeneous, multisystemic inflammatory disease characterized by inflammation of the cartilage and proteoglycan rich structures leading to cartilage damage with joint, ocular and cardiovascular involvement. "Matrilin-1-specific antibody and complement activation could mediate relapsing polychondritis." (PMID 24741569, 2014). "Relapsing polychondritis is a TH1 mediated disease and, although the target antigens are not known, human and experimental studies suggest that collagen type II and the cartilage matrix protein matrilin-1 are likely candidates." (PMID 26830405, 2016). "Matrilin-1 (Matn1) is a cartilage specific non-collagenous extracellular matrix (ECM) protein, which has been implicated in diseases such as adolescent idiopathic scoliosis and relapsing polychondritis." (PMID 27270603, 2016).
osteoarthritis (3 papers, 2016 to 2023). A noninflammatory degenerative joint disease occurring chiefly in older persons, characterized by degeneration of the articular cartilage, hypertrophy of bone at the margins and changes in the synovial membrane. "This suggests that Matn1 deficiency affects pathogenesis of post-traumatic osteoarthritis by failing to up-regulate anabolic gene expression." (PMID 27270603, 2016). "The development of spontaneous osteoarthritis in aged Matn1-4−/− mice raised the question about the contribution of the individual matrilins to the phenotype." (PMID 31963938, 2020). "Indeed, the most striking phenotype of the Matn1-4−/− mice was the development of severe osteoarthritis in aged mice." (PMID 31963938, 2020). "Previously, we had not observed age-associated osteoarthritis in single MATN1, MATN2, MATN3, or double MATN1/MATN3 deficient mice." (PMID 31963938, 2020). "The association of MATN1 with osteoarthritis was described in the Dutch but not in the British population." (PMID 31963938, 2020). "The increased severity of spontaneous osteoarthritis in the Matn1-4−/− mice might be a consequence of the compromised biomechanical properties of the articular cartilage ECM." (PMID 31963938, 2020).
idiopathic scoliosis (2 papers, 2006 to 2025). A scoliosis with no known cause. "We selected the gene encoding for the protein Matrilin-1 (MATN1 gene) as a candidate gene for human idiopathic scoliosis, by reviewing mouse mutations with phenotypes affecting the musculoskeletal system and considering only those which presented synteny conservation between mouse and man." (PMID 17176459, 2006). "The objective of this study was to assess a linkage disequilibrium between the matrilin-1 (MATN1) gene and the idiopathic scoliosis (IS)." (PMID 17176459, 2006).
rheumatoid arthritis (2 papers, 2006 to 2020). A chronic, systemic autoimmune disorder characterized by inflammation in the synovial membranes and articular surfaces. "The neoexpression of MATN1 was also observed in the cartilage of OA or rheumatoid arthritis patients, and MATN2 was recently observed in total knee arthroplasty and suggested as a biomarker for OA." (PMID 31963938, 2020). "Previous studies in human rheumatoid arthritis and RP patients and the collagen-induced arthritis models have shown antibody responses to a variety of collagens, particularly CII, as well as cartilage matrix proteins such as matrilin-1, especially during the acute phase of the disease." (PMID 16872515, 2006).
Autoimmunity (1 paper, 2020). The occurrence of an immune reaction against the organism's own cells or tissues. "To address the hypothesis that autoimmunity against matrilin-1 is involved in the pathogenesis of localized tracheobronchial RPC, we evaluated the expression level of matrilin-1 in a tracheal and auricular specimen from this patient." (PMID 32016169, 2020).
prediabetes (1 paper, 2022). "We found two susceptibility loci in MRPS6/SLC5A3 genes associated with 2hPG, six loci in LINC01648, MATN1, CRAT37, and SLCO3A1 genes associated with HbA1C, and five loci in TRPM3/TMEM2 and MLYCD/OSGIN1 correlated to BMI in Hainan prediabetes." (PMID 35299963, 2022). "In our study, we found that five novel loci in MATN1 gene were related to HbA1C in prediabetes." (PMID 35299963, 2022).
cancer (1 paper, 2010). A tumor composed of atypical neoplastic, often pleomorphic cells that invade other tissues. "To date, none of the 6 other HRneg/Tneg signature genes not functionally linked to chemokine pathways (PRRG3, RFX7, MATN1, SSX3, HRBL, and ZNF3) has shown any reported association with cancer." (PMID 20946665, 2010).
MATN1 also shares sentences with these, for which no sentence is quoted: adolescent idiopathic scoliosis (3 papers); co-infection (2); infection (2); myocarditis (2); degenerative diseases (1); diabetes (1); hematological disease (1); hypercoagulability (1); joint disease (1); juvenile idiopathic arthritis (1); multiple epiphyseal dysplasia (1); pseudoachondroplasia (1); schizophrenia (1); Sepsis (1); systemic sclerosis (1).